RNU6-974P (RNA, U6 small nuclear 974, pseudogene)
Gene: Small nuclear RNA gene on chromosome X (82,001,220 to 82,001,327, reverse strand). Ensembl gene ENSG00000206826.
Homologues: Orthologues: chimpanzee U6 (97% identical), macaque U6 (93% identical), rat U6 (82% identical), mouse Gm26011 (70% identical). Paralogues in human: RNU6-1152P (86% identical), RNU6-211P (86% identical), RNU6-1145P (85% identical), RNU6-166P (85% identical), RNU6-41P (85% identical), RNU6-73P (85% identical), RNU6-812P (85% identical), RNU6-820P (85% identical), RNU6-144P (84% identical), RNU6-15P (84% identical), RNU6-20P (84% identical), RNU6-31P (84% identical), and 1285 more.